SIGLEC15 (sialic acid binding Ig like lectin 15)
Description:
Binds sialylated glycoproteins.
Synonyms: Siglec-15; CD33L3; HsT1361
Tractability: Antibody: its Gene Ontology location is reachable by antibodies, with high confidence; UniProt predicts a signal peptide or a membrane-spanning region.
Target class: Adhesion
Gene: Protein-coding gene on chromosome 18 (45,825,675 to 45,844,094, forward strand). Ensembl gene ENSG00000197046.
Subcellular location: Membrane
Subcellular location (Human Protein Atlas): Golgi apparatus; Nucleoplasm
Pathways (Reactome):
Immune System: DAP12 interactions
Gene Ontology:
Molecular function: protein binding
Biological process: regulation of actin cytoskeleton organization; regulation of bone resorption; regulation of osteoclast development
Cellular component: plasma membrane; membrane; protein-containing complex
Genetic constraint (gnomAD): Loss-of-function variants: 30 observed, 18.24 expected, observed/expected ratio (o/e) 1.65, 90% interval 1.21 to 1.95. The synonymous counts are far from expectation, so gnomAD's model fits this gene poorly and the ratio says little. Missense variants: 479 observed, 348.62 expected, observed/expected ratio (o/e) 1.37, 90% interval 1.27 to 1.48. Synonymous variants: 201 observed, 145.54 expected, observed/expected ratio (o/e) 1.38, 90% interval 1.23 to 1.55.
Homologues: Orthologues: chimpanzee SIGLEC15 (98% identical), macaque SIGLEC15 (94% identical), dog SIGLEC15 (84% identical), pig SIGLEC15 (82% identical), mouse Siglec15 (81% identical), rat Siglec15 (80% identical), rabbit SIGLEC15 (76% identical), zebrafish bckdhbl (13% identical). Paralogues in human: SIGLEC5 (25% identical), CD33 (24% identical), SIGLEC10 (23% identical), SIGLEC8 (23% identical), SIGLEC1 (22% identical), SIGLEC7 (22% identical), SIGLEC11 (21% identical), SIGLEC14 (21% identical), SIGLEC9 (21% identical), SIGLEC12 (20% identical), SIGLEC6 (19% identical), CD22 (16% identical), and 4 more.
Diseases named in the same sentence as SIGLEC15 in open-access papers:
SIGLEC15 is named in the same sentence as 59 diseases in open-access papers, as found by Europe PMC text mining. Sharing a sentence is not in itself a finding about the gene and the disease. The quoted sentences say what the papers report.
glioma (13 papers, 2022 to 2025). A benign or malignant brain and spinal cord tumor that arises from glial cells (astrocytes, oligodendrocytes, ependymal cells). "Recent research indicates that SIGLEC15 is specifically overexpressed in the immunosuppressive microenvironment of glioma and is associated with the polarization of tumor-associated macrophages (TAMs), making it a promising pan-cancer immunotherapeutic target." (PMID 40661083, 2025). "This evidence suggests that high levels of Siglec15 expression are associated with poor prognosis in patients with glioma." (PMID 37325664, 2023). "The log rank test showed that Siglec15 overexpression correlated with reduced OST in patients with gliomas(P < 0.001)." (PMID 37325664, 2023). "In our research, that Siglec15 is higher expressed in glioma than in normal tissues, which is the same as lung, break, head, and neck square cell carcinoma and bladder cancer." (PMID 37325664, 2023). "We find that Siglec15 overexpression is an unfavorable prognostic biomarker and potentially plays a significant role in the tumor microenvironment of gliomas." (PMID 37325664, 2023). "The aim of the present study is to explore the prognostic value and immunotherapeutic possibilities of Siglec15 in gliomas using bioinformatics and clinicopathological methods." (PMID 37325664, 2023). "In the TME of gliomas, Siglec15 expression substantially alters immune cell infiltration, leading us to explore its cellular basis and distribution." (PMID 37325664, 2023). "First, Siglec15 mRNA expression levels were analysed in glioma tissues and normal brain tissues using data obtained from the TGGA, CGGA, and GEO databases." (PMID 37325664, 2023). "Taken together, these findings demonstrated a positive correlation between high Siglec15 expression and the malignant phenotype, poor treatment efficacy, and worse clinical outcomes in gliomas." (PMID 37325664, 2023). "The results revealed that the OS of glioma patients with increased Siglec15 expression levels was unfavorable according to Kaplan−Meier survival analysis of TCGA database (P < 0.001) and CGGA database (P < 0.001)." (PMID 37325664, 2023). "Bioinformatics analyses showed that high Siglec15 levels predicted poor clinical prognosis and adverse recurrence time in glioma patients." (PMID 37325664, 2023). "To investigate the role of Siglec15 in immune modulation, we examined the relationship between Siglec15 expression and immunoregulatory molecules in gliomas." (PMID 37325664, 2023). "To investigate the potential biological role of Siglec15 in gliomas, we identified DEGs between patients with high and low Siglec15 expressions." (PMID 37325664, 2023). "In the present study, a comprehensive analysis of Siglec15 mRNA and protein levels in gliomas is presented herein by bioinformatics methods and immunohistochemistry, respectively." (PMID 37325664, 2023). "We further analyzed the expression distribution of immune checkpoints gene (including CD274, CTLA4, HAVCR2, LAG3, PDCD1, PDCD1LG2, TIGIT, and SIGLEC15) in glioma tissues and normal brain tissues using the TCGA database." (PMID 36915038, 2023). "Siglec15 overexpression is common in gliomas and predicts an adverse recurrence time and overall survival time." (PMID 37325664, 2023). "It is reasonable to predict that Siglec15 is involved in glioma drug resistance through modulating the immune response." (PMID 37325664, 2023). "It was apparent that the elevated expression level of Siglec15 relates to adverse prognosis and immune response in glioma patients, and we subsequently elaborated on the effect of Siglec15 in reshaping the tumor microenvironment." (PMID 37325664, 2023). "The data showed that the mRNA expression levels of CD68, CD163 and SIGLEC15 were higher in tumor tissues than in normal tissues across a broad spectrum of human cancers, including glioma." (PMID 37234161, 2023).
glioma (continued). "To validate these results, we counted 29 immune components in 698 glioma samples from TCGA using ssGSEA and compared the level of immune infiltration between the high and low Siglec15 expression groups." (PMID 37325664, 2023). "In our study, Siglec15 was broadly and positively correlated with immune checkpoints that have been reported as potential biomarkers of glioma, such as PD1, PDL1, PDL2, Lag3, CTLA4, TIGIT, CD276 (B7-H3), IDO1 and CD47." (PMID 37325664, 2023). "The outcomes consistently revealed that patients with gliomas with the higher Siglec15 expression had significantly the poorer OS compared to those with a low Siglec15 level in subgroups including age, sex, 1p/19q status, and primary therapy outcome." (PMID 37325664, 2023). "First, we calculated the immune scores, tumorpurity, stromal scores and estimate scores, and these three scores were all positively correlated with Siglec15 expression (p <0.0001) among patients with glioma." (PMID 37325664, 2023). "Siglec15 is a potential target for immunotherapy and a potential TAMs regulator that is involved in the suppressed immunomicroenvironment in gliomas." (PMID 37325664, 2023). "The bioinformatics approach was used to examine Siglec15 mRNA expression in gliomas based on TCGA, CGGA, and GEO datasets." (PMID 37325664, 2023). "The expression of Siglec15 in various grades of glioma is shown in." (PMID 37325664, 2023). "In addition, prognostic significance of the Siglec15 mRNA and protein overexpressions in glioma patients were analysed." (PMID 37325664, 2023). "Since high Siglec15 expression may be predictive of the malignant phenotype of gliomas, we subsequently investigated the predictive value of Siglec15 expression in the clinical prognoses of glioma patients." (PMID 37325664, 2023). "In addition, the number of Siglec15+ CD163+ cells was higher in WHO grade IV gliomas than in grade II and III gliomas." (PMID 37325664, 2023). "First, we compared Siglec15 expression between the initial and recurrent glioma tissues and between the patients with relatively malignant (progressive disease [PD]) and benign (stable disease [SD], complete response [CR] or partial response [PR]) clinical courses." (PMID 37325664, 2023). "In addition, further evaluation using immune scores, matrix scores and evaluation scores also supported the relationship between Siglec15 expression and glioma immunity." (PMID 37325664, 2023). "In addition, we completed GSEA to determine the possible biological functions of Siglec15 in gliomas." (PMID 37325664, 2023). "However, the role of Siglec15 in glioma remains unreported, and a better understanding of the function of Siglec15 in glioma will contribute to the further development of cancer immunotherapies." (PMID 37325664, 2023). "Apart from this, the expression of Siglec15 on glioma cells and immune cells may mediate immune escape through cell adhesion." (PMID 37325664, 2023). "Nonetheless, little is known about the expression and role of Siglec15 in gliomas." (PMID 37325664, 2023). "Next, we analysed the impact of the Siglec15 expression level on the OS of glioma patients." (PMID 37325664, 2023). "The Siglec15 protein expression and its prognostic impact in 92 glioma samples were explored using immunohistochemistry Next, the relationships between Siglec15 expression and infiltrating immune cells, immune regulators and multiple immune checkpoints were analysed." (PMID 37325664, 2023). "Finally, the potential mechanism of Siglec15 in the regulation of the immunosuppressive microenvironment of gliomas was explored using bioinformatics methods." (PMID 37325664, 2023). "Our data revealed a significant correlation between the expression levels of immune checkpoint molecules (CD274, CTLA4, HAVCR2, LAG3, PDCD1, PDCD1LG2, TIGIT, and SIGLEC15) and RAB32 in high-grade gliomas (HGG)." (PMID 39668831, 2024).
glioma (continued). "Siglec15 protein overexpression was also found to be an independent prognostic indicator detrimental to the PFST and OST of glioma patients." (PMID 37325664, 2023). "Furthermore, We report here in for the first time that Siglec15 is upregulated and associated with clinicopathological features such as ageing, higher WHO grade, IDH wildtype, 1p/19q non-coding, reduced PFST and OST, and infiltrating immunosuppressive cells in gliomas." (PMID 37325664, 2023). "In the immunohistochemical study serving as a validation set, Siglec15 protein overexpression was found in 33.3% (10/30) of WHO grade II, 56% (14/25) of WHO grade III, and 70.3% (26/37) of WHO grade IV gliomas respectively." (PMID 37325664, 2023). "Thus, Siglec15 may serve as a potentially pivotal immune checkpoint for glioma." (PMID 37325664, 2023). "To validate the expression of Siglec15 and its impact on PFST and OST in gliomas, we subsequently performed immunohistochemistry in a series of glioma patients who received surgical resection in our hospital." (PMID 37325664, 2023). "In more details, overexpression of Siglec15 was found in 33.3% (10/30) of WHO grade II, 56% (14/25) of WHO grade III, and 70.3% (26/37) of WHO grade IV gliomas, respectively." (PMID 37325664, 2023). "It was found that Siglec15 transcript levels were elevated in gliomas compared with normal brain tissues (P < 0.05)." (PMID 37325664, 2023). "Siglec15 expression was found to be higher in recurrent gliomas as well as in those that did not respond to conventional resistance." (PMID 37325664, 2023). "Immunohistochemical analysis revealed that Siglec15 was not highly expressed in normal brain tissues but was overexpressed in 54.3% (50/92) of total gliomas." (PMID 37325664, 2023). "Indeed, the expression of A3C displayed positive correlations with CD274, PDCD1, PDCD1LG2, SIGLEC15, CTLA4, HAVCR2, and GZMB in glioma (P < 0.05)." (PMID 37809064, 2023). "It was evident that SIGLEC15, LAG3, and PDCD1 were highly expressed in glioma." (PMID 35663965, 2022). "Finally, to investigate the predictive performance of HAUS1 based on the infiltration levels of immune cells in glioma, ROC curves were generated to compare the AUC values of HAUS1, PD-L1, CTLA-4, and Siglec15." (PMID 35865089, 2022). "Siglec15 was found to be upregulated in 1p/19q noncodeletion glioma tissues (P < 0.001)." (PMID 37325664, 2023). "Correspondingly, Siglec15 could potentially interact with immune-related checkpoints, including PD1, PDL1, PDL2 and CD276 (B7-H3), implying a pivotal immunoregulatory role of Siglec15 in the glioma immune microenvironment." (PMID 37325664, 2023). "Finally, the AUC values of Siglec15, CTLA-4, PD-L1 and TP53I13 were compared, and the ROC curve was calculated to evaluate whether TP53I13 could predict the immune infiltration of glioma." (PMID 36275718, 2022).
bladder cancer (8 papers, 2021 to 2026). "In summary, here we characterized high level of Siglec15 in human bladder cancer, which was relatively predictive of both tumor stages and overall prognosis." (PMID 38468240, 2024). "In this study, we demonstrated that bladder cancer (BLCA) is a suitable candidate for anti-Siglec15 immunotherapy." (PMID 33537076, 2021). "In thirty paired samples consisting of bladder cancer and normal tissues, Siglec15 was found to be significantly and more highly expressed in cancer tissues than in normal tissues." (PMID 33537076, 2021). "Siglec15 was also expressed in various cancer cell lines, including bladder cancer cell lines, based on the screening of expression data from BioGPS and CCLE databases." (PMID 33537076, 2021). "Previous studies have employed bioinformatic tools to detect and validate promising molecular targets in cancers, such as Siglec15 in bladder cancer." (PMID 34150627, 2021). "SIGLEC15 (sialic acid-binding immunoglobulin-type lectin 15) is an emerging immunosuppressive transmembrane protein that is highly expressed in various solid tumors, including pancreatic cancer, thyroid cancer, bladder cancer, and glioma." (PMID 41158758, 2026). "This study demonstrated that bladder cancer may be a suitable candidate for anti-Siglec15 immunotherapy." (PMID 33537076, 2021). "Therefore, we hypothesized that Siglec15 expressed from bladder cancer cells may decrease the infiltration level of macrophages and monocytes by downregulating the recruiting ability of macrophages." (PMID 33537076, 2021). "Bladder cancer with high Siglec15 expression was not sensitive to cancer immunotherapy, but exhibited a higher incidence of hyperprogression." (PMID 33537076, 2021). "Second, the results of our study suggest that Siglec15 is mainly expressed in bladder cancer cells rather than macrophages." (PMID 33537076, 2021). "However, pan-cancer anti-Siglec15 treatment is not yet validated and the potential role of Siglec15 in bladder cancer (BLCA) remains elusive." (PMID 33537076, 2021). "In hepatocellular carcinoma (HCC) and bladder cancer (BLCA), elevated SIGLEC15 expression is correlated with a non-inflammatory TME and confers resistance to immunotherapy." (PMID 41158758, 2026).
breast carcinoma (8 papers, 2021 to 2026). "Elevated SIGLEC15 expression was associated with favorable outcomes in breast cancer patients." (PMID 41158758, 2026). "This study comprehensively analyzed and elaborated the function and related mechanism of SIGLEC15 in breast cancer." (PMID 41158758, 2026). "Through integrated analysis of database data, clinical samples, and in vivo/in vitro experiments, we comprehensively elucidated the role of SIGLEC15 in breast cancer, particularly in triple-negative breast cancer." (PMID 41158758, 2026). "Mechanistically, SIGLEC15 expression was found to inhibit the EMT pathway in breast cancer cells, thereby impeding the transdifferentiation of malignant cells into mesenchymal-like phenotypes." (PMID 41158758, 2026). "Contrary to its established role as a prognostic marker in luminal breast cancer, we discovered that SIGLEC15 exhibits dual functionality in TNBC, simultaneously regulating tumor biological behavior and immune modulation within the TME." (PMID 41158758, 2026). "These function experiments collectively demonstrated that SIGLEC15 suppresses breast cancer cell EMT progression and metastatic capacity." (PMID 41158758, 2026). "In breast cancer, SIGLEC15 is overexpressed in both tumor cells and tumor-infiltrating immune cells, where its expression is correlated with advanced disease stage, lymph node metastasis, and unfavorable clinical outcomes." (PMID 41158758, 2026). "Conversely, the use of anti-Siglec15 therapy reduces the occurrence of secondary metastases and enhances survival rates in cases of breast cancer bone metastasis." (PMID 39148909, 2024). "We also found that SIGLEC15 mRNA was most expressed in breast cancer with the luminal subtype and least in the basal-like subtype." (PMID 39541298, 2024). "In subsequent mouse animal model studies, it was discovered that apoptotic bodies derived from osteoclasts in the bone microenvironment inhibit the activation of CD8 T cells through Siglec15, thereby promoting the metastasis of breast cancer." (PMID 39148909, 2024). "The dataset GSE48390 study also confirmed that high expression of SIGLEC15 is a protective factor of patients with Han Chinese breast cancer." (PMID 39541298, 2024). "In summary, our research reveals SIGLEC15 as a protective agent in breast cancer progression, with the potential to predict the luminal subtype and low grade of breast cancer, especially the invasive ductal subtype." (PMID 39541298, 2024). "Contrary to general assumptions, our data suggest that SIGLEC15 might act as a beneficial factor that positively modulates immune responses in the context of breast cancer." (PMID 39541298, 2024). "In our study, SIGLEC15 mRNA emerged as a prognostic marker for breast cancer patients." (PMID 39541298, 2024). "However, the role of SIGLEC15 in breast cancer progression needs to be investigated and confirmed." (PMID 39541298, 2024). "However, further research is required to elucidate the role of SIGLEC15 in breast cancer." (PMID 39541298, 2024). "In inflamed cancer types including breast cancer, NcDase expression correlated strongly with the expression of the markers of immune regulation (CTLA4, LAG3, PDCD1, SIGLEC15)." (PMID 38302493, 2024). "After a comprehensive analysis of the expression data from TCGA, GTEx, and Oncomine databases, we found that Siglec15 was highly expressed in the majority of cancers such as BLCA and breast cancer (BRCA) compared with normal tissues." (PMID 33537076, 2021). "SIGLEC15 and YTHDF1 are overexpressed in breast cancer and especially non-basal-like subtype." (PMID 34717291, 2021).
thyroid cancer (7 papers, 2021 to 2024). "Particularly, Siglec‐15 expression in brain cancer and thyroid cancer was significantly up‐regulated." (PMID 38725348, 2024). "SIGLEC-15 is expressed on the surface of myeloid cells, and the mRNA of SIGLEC-15 is upregulated in various cancers like bladder, kidney, lung and liver cancers, colon cancer, endometrioid cancer, and thyroid cancer." (PMID 34367975, 2021). "In the present study, we aimed to decipher the comprehensive picture of the role of SIGLEC15 in thyroid carcinoma (THCA) by datamining the well-known multi-omics databases, such as The Cancer Genome Atlas (TCGA) and Gene Expression Omnibus (GEO), and validated it in our own dataset by experiments." (PMID 36159823, 2022). "Consistent with our result, previous studies through integrative data mining of SIGLEC15 mRNA expression in human tumors showed that higher SIGLEC15 levels were observed in colon adenocarcinoma and thyroid carcinoma, colon adenocarcinoma, esophageal carcinoma and thyroid carcinoma." (PMID 36159823, 2022).